HTT (huntingtin)
Diseases named in the same sentence as HTT in open-access papers (continued):
Sharing a sentence is not in itself a finding about the gene and the disease.
Huntington disease (continued). "Superficially these inclusions are similar to those formed by polyglutamine (polyQ)-expanded Huntingtin exon 1 (Httex1) in Huntington’s disease." (PMID 32857759, 2020). "RTP801/REDD1 is a stress-responsive protein that mediates mutant huntingtin (mhtt) toxicity in cellular models and is up regulated in Huntington’s disease (HD) patients’ putamen." (PMID 32732871, 2020). "Dysregulation of ATM signalling has also been addressed to Huntington’s disease (HD), a genetic neurodegenerative disorder caused by a CAG-repeat expansion in the first exon of the HTT gene encoding the huntingtin protein." (PMID 32858941, 2020). "With respect to ATXN3, the recent identification of Huntingtin, the polyQ protein responsible for Huntington's disease, as a substrate adaptor for autophagy, appears to be most relevant." (PMID 31625269, 2020). "For the first time in studies of Huntington's disease, we also assessed multiparametric imaging, providing brain estimates of myelin and iron, as well as CSF measurements of total huntingtin." (PMID 32470422, 2020). "A similar observation was recently made for Huntington’s disease in relation to huntingtin aggregates." (PMID 32867861, 2020). "Mounting evidence suggests that mutant huntingtin (mHtt) influences directly mitochondrial homeostasis contributing to Huntington's disease (HD) pathogenesis." (PMID 33537304, 2020). "Preliminary studies show a protective function of TMX3 against neuronal atrophy in mice models for Huntington’s disease, a progressive brain disorder caused by an inherited CAG trinucleotide repeat expansion in the huntingtin (HTT) gene." (PMID 32878123, 2020). "Intrathecal administration to patients with Huntington’s disease was shown to be safe, with dose-dependent reductions in mutant huntingtin." (PMID 32087199, 2020). "The unique, developmentally necessary huntingtin protein (HTT) of Huntington’s disease, has emerged as a possible CaMBP." (PMID 32054133, 2020). "Intracellular inclusion bodies of mutant Huntingtin protein are a key feature of Huntington’s disease brain pathology." (PMID 32735619, 2020). "The huntingtin-associated protein 40 (HAP40) abundantly interacts with huntingtin (HTT), the protein that is altered in Huntington’s disease (HD)." (PMID 33297953, 2020). "Huntington Disease (HD) is an incurable and fatal neurodegenerative condition caused by dominant CAG trinucleotide expansion mutations in exon 1 of the Huntingtin gene." (PMID 32735619, 2020). "Huntington’s disease is a progressive, autosomal dominant, neurodegenerative disorder caused by an expanded CAG repeat in the huntingtin gene." (PMID 32967102, 2020). "The chaperonin TRiC/CCT is associated with protein aggregation in disease, in particular in Huntington’s Disease, where it can bind to specific subunits of the huntingtin protein and modulate its aggregation." (PMID 33330614, 2020). "Targeting HTT by means of lowering its expression is already being tested in the context of Huntington’s disease therapy." (PMID 33057179, 2020). "Treating zebrafish models of tauopathies or Huntington’s disease with a PDE5 inhibitor reduced the levels of the mutant huntingtin and tau proteins, cell death, and the resulting morphological abnormalities." (PMID 32513741, 2020). "In Huntington’s disease (HD), proteolytic processing generates toxic N-terminal huntingtin (HTT) fragments that preferentially kill striatal neurons." (PMID 32444599, 2020). "Huntington’s disease (HD) is a genetic, autosomal dominant disorder caused by a CAG trinucleotide repeat expansion in the Huntingtin gene, encoding for the toxic mutant Huntingtin protein (mHTT)." (PMID 33033167, 2020). "Huntington’s disease (HD) is an incurable and progressive neurodegenerative disease caused by the expansion of CAG repeats in exon 1 of the huntingtin gene (HTT)." (PMID 32182692, 2020).
Huntington disease (continued). "Huntington Disease (HD), a neurodegenerative disorder caused by CAG repeats in the Huntingtin gene, leads to the accumulation of the mutant protein and an associated neuronal degeneration and gliosis." (PMID 32070434, 2020). "KCC2 interacts with Huntingtin and is downregulated in Huntington’s disease (HD), which contributed to GABAergic excitation and memory deficits in the R6/2 mouse HD model." (PMID 31963584, 2020). "Trials using antisense oligonucleotide technology to lower Huntingtin levels in Huntington’s disease (HD) are currently ongoing." (PMID 32245050, 2020). "In Huntington’s disease (HD), the mutant Huntingtin (mHTT) is postulated to mediate template-based aggregation that can propagate across cells." (PMID 33219289, 2020). "Huntington disease (HD) is a rare genetic autosomal dominant neurodegenerative syndrome triggered by expanded CAG repeats in the huntingtin gene, which leads to pathological elongation of huntingtin with a polyglutamine tract." (PMID 32390854, 2020). "Huntington’s disease (HD) is an autosomal dominant disorder, caused by CAG trinucleotide repeat expansion of the gene encoding huntingtin (HTT)." (PMID 33266310, 2020). "Huntington’s disease (HD) is characterized by the accumulation of the huntingtin protein (htt) and disturbances in axonal transport, resulting in cognitive decline, dementia, and impairment in motor coordination." (PMID 33041780, 2020). "The identification of Huntington’s disease (HD) pathway in the cilia interactome is also notable given that the protein huntingtin (HTT) localizes to the centrosome and plays an important role in ciliogenesis." (PMID 32973177, 2020). "A number of studies found that genetic variants other than those controlling the CAG repeat size of the polyQ-expanded huntingtin (Htt) are capable of modifying the pathogenesis of Huntington’s disease (HD)." (PMID 32093691, 2020). "Mitochondrial deregulation has gained increasing support as a pathological mechanism in Huntington’s disease (HD), a genetic-based neurodegenerative disorder caused by CAG expansion in the HTT gene." (PMID 33072759, 2020). "In the BACHD mouse model of Huntington’s disease (HD), deletion of the N17 domain of the Huntingtin gene (BACHDΔN17, Q97) has been reported to lead to nuclear accumulation of mHTT and exacerbation of motor deficits, neuroinflammation and striatal atrophy." (PMID 32574176, 2020). "Huntington disease (HD) is a debilitating and fatal neurodegenerative disorder caused by a CAG trinucleotide repeat expansion in the huntingtin (HTT) gene." (PMID 33250715, 2020). "Huntington disease (HD) is a fatal neurodegenerative genetic disorder, thought to reflect a toxic gain of function in huntingtin (Htt) protein." (PMID 31737741, 2019). "In Huntington ́s disease (HD), the polyglutamine-containing domain of the abnormal huntingtin protein was able to bind to HAT domains, therefore influencing the acetyltransferase activity." (PMID 31242699, 2019). "This is a characteristic of tau protein in Alzheimer’s disease and several tauopathies associated with tau unfolding, α-synuclein in Parkinson’s disease, and huntingtin in Huntington disease." (PMID 31572186, 2019). "To validate this system, we analysed neurons expressing a disease-associated version of huntingtin (HTT586Q138-EGFP), and observed that they displayed hallmarks of Huntington’s disease and died sooner than controls." (PMID 31069265, 2019). "Our work clarifies the structural features responsible for heterogeneous huntingtin aggregation with possible implications to contrast the prion-like spreading of Huntington’s disease." (PMID 31110208, 2019). "In Huntington’s disease (HD), while the ubiquitously expressed mutant Huntingtin (mtHTT) protein primarily compromises striatal and cortical neurons, glia also undergo disease-contributing alterations." (PMID 31316341, 2019).
Huntington disease (continued). "This includes α-synuclein in PD or transactivation response element DNA-binding protein 43 (TDP-43) in ALS, as well as the polyQ disease proteins huntingtin in Huntington disease (HD) and ataxin-3 in Machado-Joseph disease (MJD)." (PMID 30895192, 2019). "Huntington’s disease (HD) is a neurodegenerative disease triggered by expansion of polyglutamine repeats in the protein huntingtin." (PMID 30941013, 2019). "Huntington disease is a neurodegenerative disease characterized by a polymorphic tract of polyglutamine repeats in exon 1 of the huntingtin protein, which is thought to be responsible for protein aggregation and neuronal death." (PMID 31632982, 2019). "We also tested MitoPQ in a Huntington's disease cellular model where it increased mutant huntingtin (mHtt) aggregation." (PMID 30389496, 2019). "Mutations resulting in repeat expansion are also associated with protein aggregation such as the ALS/FTD linked gene C9ORF72, or polyglutamine (polyQ) expansions seen in several disorders, most prominently Huntingtin (HTT) in Huntington’s Disease (HD)." (PMID 31783880, 2019). "Using the ribozyme switches we established inducible C. elegans polyglutamine Huntington’s disease models exhibiting ligand-controlled polyQ-huntingtin expression, inclusion body formation, and toxicity." (PMID 30700719, 2019). "Huntington disease (HD), a devastating neurodegenerative condition with a prevalence of ∼1/10000, is caused by the expansion of a CAG/CAA repeat in exon one of the HTT gene." (PMID 31607598, 2019). "Huntington's disease (HD) is an autosomal dominant progressive neurodegenerative disorder, caused by a CAG/polyglutamine (polyQ) repeat expansion in the Huntingtin (HTT) gene." (PMID 31828084, 2019). "Variable, glutamine-encoding, CAA interruptions indicate that a property of the uninterrupted HTT CAG repeat sequence, distinct from the length of huntingtin’s polyglutamine segment, dictates the rate at which Huntington’s disease (HD) develops." (PMID 31398342, 2019). "Huntington’s disease (HD) is a rare genetic neurodegenerative disorder caused by the mutation of the IT15 gene, which codes the huntingtin protein located on the short arm of chromosome 4." (PMID 31262100, 2019). "Although Huntington’s disease is a cell autonomous genetic disorder, recent experimental work, both in vitro and in vivo, shows that mutant huntingtin proteins can be transmitted to neighboring cells with potential prion-like infection and propagation." (PMID 31110208, 2019). "The TDP-43 and PGRN-mediated effects on the huntingtin toxicity need further investigation using mammalian models and Huntington's disease patients." (PMID 30837838, 2019). "Huntington’s disease (HD) is a monogenic neurodegenerative disease produced by the expression of mutant huntingtin (htt) protein with expanded glutamine repeats in the N-terminal portion of the protein." (PMID 30899454, 2019). "Huntingtin (HTT) is a 348 kDa protein mainly known for its pathological role in Huntington’s disease (HD)." (PMID 31109380, 2019). "Huntington disease (HD; OMIM 143100) is an inherited neurodegenerative disease caused by a CAG repeat expansion in exon 1 of the huntingtin (HTT) gene located on chromosome 4p16.31,2." (PMID 31712634, 2019). "Huntington’s disease (HD) is an autosomal dominant, progressive, neurodegenerative disorder caused by a CAG repeat expansion within exon 1 of the huntingtin gene (HTT), that encodes a polyglutamine (polyQ) tract in the HTT protein." (PMID 31282030, 2019). "Mutations in the HTT gene, consisting of expansion of CAG triplets, cause the Huntington’s disease (HD), one of the major neurodegenerative disorders." (PMID 30850940, 2019). "Huntington’s Disease (HD) is a fatal neurodegenerative disorder caused by a CAG repeat expansion, resulting in a mutant huntingtin protein." (PMID 31722751, 2019).
Huntington disease (continued). "Inflammation significantly impacts the progression of Huntington's disease (HD) and the mutant HTT protein determines a pro‐inflammatory activation of microglia." (PMID 30585395, 2019). "Huntington’s disease (HD) is a progressive and fatal neurodegenerative disorder caused by the trinucleotide repeat expansion (CAG) in exon 1 of the huntingtin (HTT) gene." (PMID 31398826, 2019). "Huntington's disease (HD) is a neurodegenerative disease, hallmarked by the formation of intracellular aggregates induced by polyglutamine (polyQ) expanded huntingtin protein fragments." (PMID 31482094, 2019). "Huntington’s disease (OMIM: 143100) AO is mainly (about 60%) determined by the length of the CAG repeat expansion (CAGexp) in the HTT gene." (PMID 29791508, 2018). "Huntington's disease (HD) is a progressive and autosomal dominant neurodegenerative disorder that is caused by a CAG repeat expansion in exon 1 of the huntingtin (htt) gene on the short arm of chromosome 4." (PMID 30518638, 2018). "Huntington’s disease is a devastating, dominantly inherited neurodegenerative disorder caused by expansion of the number of CAG triplets in the first exon of the huntingtin (htt) gene." (PMID 29523177, 2018). "Such hungry codon-mediated frameshifting has also been proposed to be responsible for observed −1 frameshifting of Huntingtin in Huntington’s disease due to the extensive use of glutamine CAG codon." (PMID 30518074, 2018). "Huntington disease (HD) is a dominantly inherited disorder caused by a CAG expansion mutation in the huntingtin (HTT) gene, which results in the HTT protein that contains an expanded polyglutamine tract." (PMID 28497201, 2018). "Huntington’s disease (HD) is a progressive neurodegenerative disorder primarily affecting the basal ganglia and is caused by expanded CAG repeats in the huntingtin gene." (PMID 29959348, 2018). "For example, the E3 ligase TRAF6 (tumor necrosis factor receptor-associated factor 6), associating with and ubiquitinating huntingtin protein, promotes huntingtin protein aggregate formation in Huntington’s disease." (PMID 30404641, 2018). "The time course of amyloid conversion has been studied extensively in vitro with the proteins involved in the neurodegenerative pathology of Parkinson’s disease (α-synuclein), Alzheimer’s disease (Tau) and Huntington’s disease (Huntingtin)." (PMID 29255947, 2018). "Miki and co-workers (2015) have found intranuclear aggregates of σ1Rs with huntingtin, and they reported that σ1R is involved in the degradation of intranuclear inclusions in a cellular model of Huntington’s disease." (PMID 28786032, 2018). "Huntingtin is a protein critical for induction of learning in Aplysia, and expression of mutant huntingtin induced neurological deficits in Huntington’s disease mouse models." (PMID 29996779, 2018). "Mutant huntingtin protein tends to form aggregates that are hardly degradable and became a distinctive feature of Huntington’s disease." (PMID 29435951, 2018). "Huntington disease (HD) is an autosomal dominantly inherited, neurodegenerative disorder caused by the expansion of a trinucleotide repeat (>36 CAG) in exon 1 of the huntingtin gene (HTT) on chromosome 4." (PMID 29422836, 2018). "In Huntington’s disease, expression of mutant Huntingtin (HTT) protein results in a cell-autonomous pro-inflammatory state of activation of microglia and, to a certain extent, of astrocytes." (PMID 29799467, 2018). "Huntington’s disease is an autosomal dominant progressive neurodegenerative disorder caused by an inherited, pathogenic expansion of CAG repeats in exon 1 of the huntingtin gene (HTT)." (PMID 29959348, 2018). "In Huntington’s disease, post-translational modifications of huntingtin are carried out by transglutaminase and these modifications contribute to the aggregation of the huntingtin protein." (PMID 30380624, 2018).
Huntington disease (continued). "The transgenic rat model of Huntington disease expressing a fragment of mutant HTT (tgHD rat) has been thoroughly characterized and reproduces hallmark symptoms of human adult-onset HD." (PMID 29422836, 2018). "We therefore turned to a neuronal model of Huntington’s disease, in which neurons overexpress a fragment of mutant huntingtin (Htt) carrying 96 polyglutamine residues fused to EGFP (Htt96Q-EGFP)." (PMID 29545601, 2018). "Trinucleotide (CAG) repeat expansion in the Huntingtin gene (HTT) results in the expression of misfolded Huntingtin protein (Htt), which contributes to the development of Huntington’s disease." (PMID 29346421, 2018). "Unusual −1 frameshifting without an XXXYYYZ shifty site has been reported for the CAG trinucleotide expansion region of the MJD-1 transcript in spinocerebellar ataxias 3 as well as huntingtin in Huntington’s disease." (PMID 30518074, 2018). "Perturbations in sphingolipid metabolism have been found responsible for misfolding events causing the formation of disease-specific protein isoforms such as alpha-synuclein in PD, amyloid-beta in AD and huntingtin in Huntington's disease." (PMID 29556190, 2018). "Huntington’s disease (HD) is a progressive and fatal neurodegenerative disease caused by CAG repeat expansion in the coding region of huntingtin (HTT) protein." (PMID 30149534, 2018). "HTT, alternatively called Huntington’s disease protein or, simply, HD protein (UniProtKB—ID: P42858), in vertebrates, is a highly conserved soluble 348 kDa protein." (PMID 30110961, 2018). "Induced pluripotent stem cells (iPSCs) suppress the aggregation of Huntington’s disease (HD) polyQ-expanded huntingtin (HTT)." (PMID 30038412, 2018). "Huntington’s Disease (HD) is an autosomal dominant, progressive neurodegenerative disorder caused by deleterious expansion of CAG repeats in the Huntingtin gene and production of neurotoxic mutant Huntingtin protein (mHTT)." (PMID 30118496, 2018). "Huntington’s disease (HD) age of onset (AO) is mainly determined by the length of the CAG repeat expansion in the huntingtin gene." (PMID 29791508, 2018). "Huntington’s disease (HD) is an inherited neurodegenerative disorder due to an increased number of CAG repeats of the huntingtin (HTT) gene, leading to a polyglutamine repetition at the NH2-terminal of the huntingtin protein (HTT)." (PMID 29505597, 2018). "Huntington’s disease (HD) is a fatal, progressive neurological disorder caused by a coding cytosine-adenine-guanine (CAG) expansion in the huntingtin (HTT) gene, where repeat lengths above 40 result in full penetrance of the disease." (PMID 29396492, 2018). "By contrast, Huntington’s disease (HD) presents with the nuclear accumulation of mutant Huntingtin (mHTT), which arises from the expansion of a polyglutamine (polyQ) stretch within the N-terminal domain of the HTT protein." (PMID 30486313, 2018). "Huntington Disease (HD) is an incurable autosomal dominant neurodegenerative disorder driven by an expansion repeat giving rise to the mutant huntingtin protein (mHtt), which is known to disrupt a multitude of transcriptional pathways." (PMID 29783994, 2018). "Huntington disease (HD) is an autosomal dominant, neurodegenerative disease caused by a CAG repeat extension in the HTT gene, encoding the huntingtin protein (Htt), which results in appearance of a long polyglutamine tract in the gene product." (PMID 30120672, 2018). "However, since normal and mutant huntingtin (the protein product of the Huntington’s disease gene) differ only on the polyglutamine length, unless allele-specific silencing is planned, normal huntingtin (that is neuroprotective) will also be inactivated with unknown implications." (PMID 28715425, 2017).